FLT3 (fms related receptor tyrosine kinase 3)
Diseases named in the same sentence as FLT3 in open-access papers (continued):
Sharing a sentence is not in itself a finding about the gene and the disease.
cancer (continued). "A number of resistance mechanisms against FLT3 inhibitors have been identified, including acquired resistance mutations of FLT3, other somatic mutations of cancer-related genes, and activation of alternative signaling pathways." (PMID 31692922, 2019). "In cancer cells with activating mutations in FLT3, FLT3 inhibitors or tyrosine kinase inhibitors have been shown to be effective and a number of small-molecule tyrosine inhibitors of FLT3 have been developed and trials are ongoing." (PMID 27906677, 2017). "Recent analysis of germline mutations in childhood cancers identified a FLT3 frameshift mutation in a child with E2A-fusion ALL." (PMID 27683039, 2016). "Louis, MO) for detecting somatic mutations in FLT3 and in 26 other genes that are frequently mutated in cancer." (PMID 26078355, 2015). "For the past 20 years, drug discovery efforts have pursued the development of kinase inhibitors to block the aberrant activation of kinases associated with the cancer progression, as observed for FLT3 in AML." (PMID 25837374, 2015). "Typically, cancer cells with activated FLT3 variants become reliant on FLT3 for growth, and therefore, are susceptible to FLT3-targeted inhibitors." (PMID 25837374, 2015). "Meta-analysis of microarray data from patient samples suggests that SLAP mRNA is differentially expressed in different cancers and its expression was significantly increased in patients carrying the Flt3-ITD mutation." (PMID 23300935, 2012). "Flt3 induces Ras signaling, and mutation of Flt3 is mutually exclusive with Ras mutations in human cancers suggesting that mutation of Flt3 has similar effects as Ras mutation." (PMID 18485879, 2008). "FLT3 encodes for a transmembrane receptor belonging to the tyrosine kinase receptor family, playing a pivotal role in the activation of hematopoietic stem cell proliferation, especially in cancer cells." (PMID 38944027, 2025). "This study was designed to predict and understand how certain variants affect FLT3 protein function and determine whether any of these known variants may be correlated with either an increased or decreased cancer risk." (PMID 38542393, 2024). "FLT3 mutations are an important molecular marker in a variety of cancers such as AML." (PMID 39758420, 2024). "However, clinical data showed that the F691L mutation of FLT3 would confer cancer cells with acquired resistance to certain FLT3 inhibitors." (PMID 35269825, 2022). "Similarly, co-occurrence of mutations in FLT3 with national comprehensive cancer network (NCCN)-listed gene mutations were used as predictive biomarkers." (PMID 35267471, 2022). "In our study, the frequencies of FLT3 mutations were lower in South Koreans than in Caucasians and Hispanics, suggesting that some mutational signatures that predict cancer outcomes may vary by race." (PMID 34941036, 2021). "Although the exact mechanism remains unclear, tyrosine kinase FLT3 inhibitors have been associated with significant cardiotoxicities, an important limitation in cancer therapy." (PMID 34686212, 2021). "In addition, the three final hub genes discovered are all novelly associated with cancer, especially FLT3." (PMID 33193652, 2020). "The pathogenesis of several malignant tumors are associated with the overexpression of FLT3." (PMID 33193652, 2020). "Additionally, Star 27 continues to work even when mutations arise in the cancer cells that cause resistance to other FLT3 inhibitors." (PMID 25531068, 2014). "In order for a targeted therapy to eradicate disease, the target itself must be present in the cancer stem cell, and it remains controversial whether FLT3-ITD mutations are present in the LSC." (PMID 25295230, 2014).
cancer (continued). "Importantly, PRL-3 upregulation by FLT3-ITD mutations associated with cancer progression, a phenomenon potentially explained by the PRL-3-induced activation of oncogenic transcription factor c-Jun/AP-1." (PMID 23929599, 2013). "This study was conducted to investigate the relationship between FLT3 mutations and gene expression as well as DNA methylation, aiming to identify potential new therapies for FLT3 inhibitor resistance and shed light on the impact of FLT3 mutations on the differentiation of cancer cells." (PMID 38944027, 2025). "This involved the use of small molecules that wouldshift cancer cells toward the pre-sensitive states, thereby enhancing theirresponsiveness to FLT3 inhibitor treatment." (PMID 41270153, 2025). "The FLT3 story, therefore, exemplifies both the remarkable progress and the ongoing challenges inherent in targeting kinases in cancer." (PMID 41228209, 2025). "The FLT3 story illustrates both the promise and the ongoing challenges of kinase inhibition in modern cancer care." (PMID 41228209, 2025). "In contrast, KIT D816V, FLT3 D835Y, and PDGFRA D842V are activation loop mutations commonly found in acute leukemias, gastrointestinal stromal tumors, and other cancer types." (PMID 40831936, 2025). "The FLT3-ITD mutation leads to constitutive activation of downstream signaling pathways, such as STAT5 and MAPK, promoting excessive proliferation of cancer cells and conferring resistance to chemotherapy-induced apoptosis." (PMID 41294667, 2025). "FLT3 was also found to be involved in transcriptional misregulation in cancer and its promoter region was bound by WT1 according to Genecards." (PMID 38944027, 2025). "The Asp at position 7 is the Aspβ9 (FLT3 D835, KIT D816, and PDGFRA D842) which is recurrently mutated in many cancer types." (PMID 40831936, 2025). "The structure-based functional annotation and prediction of cancer variations’ impact on biomarker proteins, including FLT3, will help in better understanding the molecular pathology of tumorigenesis and drug-resistance mechanisms." (PMID 38542393, 2024). "To identify novel genotype-specific combinatorial anti-cancer treatments in AML patients with FLT3-ITD, we employed a multidisciplinary strategy combining multiparametric analysis with literature-derived causal networks and Boolean logic modeling." (PMID 38564252, 2024). "We here demonstrated that mutant FLT3 suppressed succinyl-CoA signaling to enhance mitobiogenesis and promote cancer development." (PMID 38649537, 2024). "As a result of these mutations, the FLT3 receptor is perpetually activated in the absence of the FLT3 ligand (FLT3L), increasing proliferation and decreasing apoptosis, making FLT3 an excellent target for cancer therapies." (PMID 39273395, 2024). "In our study, we addressed the general question of how cancer cells that rely on chronic growth factor signaling bypass targeted inhibition by examining the molecular basis of drug resistance against FLT3 inhibitors in AML." (PMID 38638836, 2024). "In a phase 1 study in participants with Her2/neu-overexpressing cancers, administration of Flt3 before Her2/neu-specific peptide vaccine resulted in significantly higher IFN-γ-secreting Her2/neu-specific T cells." (PMID 38829139, 2024). "STC2 expression was mainly observed in endothelial cells, normal epithelial cells, and cancer epithelial cells, while FLT3 was primarily expressed in myeloid cells and cancer epithelial cells." (PMID 39020010, 2024). "In our study, silencing of COL6 in GBM cells induced the downregulation of genes associated with cancer-relevant pathways, including PI3K/AKT, IGF1, FLT3, PDGF, and MAPK pathways." (PMID 37505240, 2023).
cancer (continued). "Enrichment analysis disclosed downregulated genes as significantly involved in several cancer associated intracellular pathways including PI3K/AKT, IGF1, FLT3, PDGF, and MAPK, together with microenvironmental processes such as ECM and TIE2 signaling." (PMID 37505240, 2023). "In this respect, it is interesting that inhibitors of FLT3 have been approved for various cancers and have been trialed with positive effect for multiple T-cell-mediated auto-immune diseases that are genetically and/or clinically overlapping/comorbid with TD." (PMID 36674940, 2023). "In conclusion, the triple combination treatment of ASP1235, venetoclax and azacitidine has the potential to benefit AML patients, and there is a possibility to expect the combination effect of ASP1235 and venetoclax regimen in FLT3 positive cancers beyond AML." (PMID 36537913, 2022). "Co-targeting of CDK9 and FLT3 is a promising two-pronged strategy to overcome resistance as the former plays a role in the transcription of cancer cell-survival genes." (PMID 35267421, 2022). "FLT3 propagates signals in the cell to maintain cellular functional activity, and its ligand is also important for inducing cancer relapse and antitumor immune reactions." (PMID 35300397, 2022). "According to the prediction and molecular docking results presented in this study, erianin shows high potential to interact with molecules like PIK3CA, RET, KIT, ABL1, and FLT3 in cancers, all of which were found to play important roles in cancer progression." (PMID 35372513, 2022). "The drug candidate has potential to overcome cancer cell resistance to FLT3 inhibition by concurrently blocking the CDK9-mediated upregulation of cancer cell-survival genes." (PMID 35267421, 2022). "Both drugs target FLT3, are approved for treatment of different types of cancer and are currently also being investigated in clinical trials for treating AML." (PMID 34944800, 2021). "Although RTK inhibitors, especially FLT3 inhibitor-quizartinib, demonstrate single-agent efficacy by inducing complete remission in cancer patients, their utility is limited to FLT3-mutant AML patients." (PMID 34944663, 2021). "Natural phytochemical compounds have induced anti-cancer effects in FLT3-ITD overexpressing cells, suggesting that phytochemical compounds can inhibit the expression of the ITD-mutated FLT3 gene." (PMID 34959687, 2021). "Fluvastatin hinders the glycosylation of FLT3 in human and murine cells, acting as an anti-cancer agent and prolonging the survival of FLT3/ITD leukemic mouse models." (PMID 34065757, 2021). "Although FLT3 inhibitors can prolong the survival of patients harboring cancers with FLT3-ITD24, the outcome of treatment in these patients remains unsatisfactory due to insensitivity to these compounds and/or acquired drug resistance." (PMID 34035227, 2021). "Recently, novel protein interactions and downstream molecules for FLT3 which support cancer cell proliferation have been identified." (PMID 34811450, 2021). "Recurrent alterations at the same genomic site in cancer genes such as MET, MPL, FLT3, and KIT have been implicated in many different cancer types." (PMID 34068918, 2021). "They postulate that inhibition of FLT3 signaling in antileukemic targeted therapies may result in loss of this cardioprotective mechanism and lead to cardiomyocyte death, which may be a potential explanation for cardiotoxicity seen in FLT3 targeted cancer therapies." (PMID 34686212, 2021). "We focus on internal tandem duplications (ITDs) occurring in different domains of the FLT3 gene and we describe how the distinct location along the cytoplasmic domain of this transmembrane receptor influences cancer cell sensitivity to drugs." (PMID 33925552, 2021).
cancer (continued). "The upregulation and/or increased activity of cytochrome P450 enzymes (CYP3A4) has been shown to increase the drug turnover in FLT3-positive AML as well as in other cancer types." (PMID 33925552, 2021). "The aim of this invention was to evaluate all synthesized compounds on different kinases pathways signaling (p38, but also Raf, VEGFR-2, VEGFR-3, PDGFR-beta, Flt-3), all involved in ongoing cancer, in cancer progression, and in the angiogenesis process." (PMID 32751358, 2020). "Although uncoordinated 51-like kinase 1 (ULK1), which plays a central role in the autophagy pathway, has emerged as a novel therapeutic target for various cancers, its role in FLT3-ITD AML remains elusive." (PMID 32393312, 2020). "Deep valleys followed by the highest growth peaks corresponded with close approximation to the three missense mutations from known cancer genes (IDH1, IDH2, and FLT3, p value < 2.2e−16)." (PMID 32024824, 2020). "In the present study, we examined the cytotoxic effects of penfluridol in three AML cancer cell lines which harbor the FLT3-WT and FLT3-ITD." (PMID 31470848, 2019). "Of note, 1 inhibited other cancer-related targets such as FLT3, which activates the Ras/ERK signaling pathway." (PMID 31026276, 2019). "For the lymphoid-derived cancer cell lines next to the specific surface markers (e.g., CD72, LAIR) associated with T/B-cells, we identified FLT3, HOXA9, MYC, and HEXIM1 as top genes driving the difference between the samples." (PMID 31253180, 2019). "Compared with genes such as c-KIT and FLT3 (FMS-like tyrosine kinase 3), CAMs are much less frequently found to be mutated in cancer cells." (PMID 30841639, 2019). "Although single isoform specific Aurora inhibitors were developed, pan-Aurora inhibitors and even those with an additional anti-cancer pharmacology, such as fms-like tyrosine kinase 3 (FLT3) inhibition were also pursued." (PMID 30953752, 2019). "In contrast, FLT3, BRCA1, BRCA2 and PIK3R1 mutations were more frequently detected in patients carrying germline cancer-associated variants." (PMID 30850667, 2019). "There are 36 protein kinases in the Cancer Gene Census; seven of them (EGFR, ERBB2, BRAF, FLT3, PRKACA, LCK, and FGFR2) had enriched PTM/mutation domains in our study." (PMID 29695735, 2018). "Since midostaurin has only been approved for clinical use this year and given that FLT3 +-AML is a fairly rare cancer, little is known on alternative signalling pathways or the potential for combination therapy." (PMID 29699481, 2018). "Children with FLT3–ITD AML treated on Children’s Cancer Group and Pediatric Oncology Group trials fared similarly poorly with 30% 4-year EFS when treated with conventional multi-agent chemotherapy." (PMID 29209600, 2017). "Kinases Flt3, Kit (cKit) and Ret have well-documented functions in the immune system and in various cancers, while their functions in the nervous system have been explored to varying extents." (PMID 28558017, 2017). "Since the cancer-causing mutants of EGF-R, Met, Flt3 and gp130 also initiate their signals from organelles, intracellular delivery of TKIs to signaling platforms will open new fields for targeting therapy." (PMID 28192400, 2017). "Apart from the role in multidrug resistance, FLT3 also mediates pro-survival physiological processes that favor cancer growth and progression." (PMID 28858244, 2017). "In summary, FLT3 amplification in solid cancers is a frequently encountered genomic alteration in the clinic with various prevalence across cancer types." (PMID 27906677, 2017). "qRT-PCR was performed to verify GEP findings and analyze the relationship between copy number change and expression change in four well known cancer associated genes including MYC, KIT, FLT3, and PTEN." (PMID 27639374, 2016).
cancer (continued). "Mechanistic studies in MV4-11 and HCT-116 cell lines suggest that the cancer relevant targets AURKA/FLT3 are inhibited inside the cells." (PMID 27863392, 2016). "As midostaurin is a multi-target protein kinase inhibitor having a broad inhibition spectrum, it is suggested that midostaurin shows its anti-cancer effect against the target other than FLT-3." (PMID 26141684, 2015). "Scientists have recently discovered that treatments that inhibit the FLT3 enzyme can be effective against cancer." (PMID 25531068, 2014). "While different levels of expression was observed in different cancers, an upregulation of SLAP expression was found in patients carrying the Flt3-ITD mutation as compared to wild-type Flt3." (PMID 23300935, 2012). "Of special interest is a spectrum of EGFR, ABL, MET, FLT3 and KIT cancer mutations that correspond to the same structurally conserved position in the activation loop, which appeared to be mutated in at least 8 different kinases." (PMID 19834613, 2009). "In addition, co-expression analysis using the TCGA Pan-Cancer dataset via UCSC Xena revealed a positive correlation between NLRP3 and FLT3 in more than 30 different cancer types." (PMID 39875995, 2025). "Given its critical role in AML progression, FLT3 is a major target for cancer therapy." (PMID 40361130, 2025). "Conversely, in cancer cells lines without the FLT3-ITD mutation (HeLa, MCF-7, and HT1080 cells), CRBN(FLT3)-8 exhibited minimal proliferation inhibition, even at micromolar concentrations, and was significantly less effective than gilteritinib." (PMID 40793752, 2025). "The Cancer and Leukemia Group B 10603 RATIFY trial established the addition of the FLT3 inhibitor midostaurin to daunorubicin‐based 7+3 as the new standard of care for FLT3‐mutated patients." (PMID 40052282, 2025). "Collectively, our data suggest that ROS could serve as a central mediator in the adaptive response of cancer cells to hypoxia, particularly in relation to immune checkpoints in FLT3-ITD leukemic cells." (PMID 40746567, 2025). "However, FLT3’s transcript per million in AML (TPM = 342) is quite high compared to other cancers (TPM ranging 5–125)." (PMID 38542393, 2024). "To this end, we first examined the publicly available AML data (gepia.cancer-pku.cn) and found that the CSF1R gene is overexpressed in many AML patient samples, similar to several other AML-implicated targets previously, FLT3, MLL and CDK6." (PMID 38641704, 2024). "However, KW-2449 is able to induce cytotoxicity in cancer cells by targeting FLT3, ABL, and Aurora kinases." (PMID 39433736, 2024). "Among them, FLT3 had up to 27 percent of SNVs in pan-cancer analysis." (PMID 36675706, 2022). "Like many other cancers, dysregulated kinase activity is a main feature driving AML oncogenic signaling, with the most common mutations seen at diagnosis in the receptor tyrosine kinase FLT3 (20–35% patients)." (PMID 36536316, 2022). "Outside of AML, the combination treatment with ASP1235 and venetoclax might be beneficial in other types of cancers overexpressing FLT3." (PMID 36537913, 2022). "As a result, PIK3R1 and FLT3 were recognized to be mutations that were not correlated to metastasis and the recurrence of a malignant tumor." (PMID 35664766, 2022). "Collectively, our findings suggest that different components of the 19S regulatory complex in the 26S proteasome have indications for OS and may serve as prognostic biomarkers and novel therapeutic targets in FLT3-mutated AML and other types of cancers." (PMID 36498916, 2022).